NXNL1 (nucleoredoxin like 1)
Description:
[Isoform 1]: Thioredoxin-like protein that protects retinal rod and cone photoreceptors against oxidative stress and photo-oxidative damage. Plays a role in the inhibition of TAU phosphorylation and protects TAU against oxidative stress in the retina (By similarity). Acts as a reducing system for MSRA, facilitating the repair of oxidized proteins such as alpha-crystallin (CRYAA/CRYAB) and cytochrome c (CYCS) in the lens during oxidative stress conditions. [Isoform 2]: Plays an important role in retinal cone photoreceptor survival. In association with glucose transporter SLC16A1/GLUT1 and BSG, promotes retinal cone survival by enhancing aerobic glycolysis and accelerating the entry of glucose into photoreceptors. May play a role in cone cell viability, slowing down cone degeneration, does not seem to play a role in degenerating rods (By similarity).
Synonyms: RdCVF; TXNL6
Tractability: No criterion of Open Targets' tractability assessment is met for any kind of drug.
Gene: Protein-coding gene on chromosome 19 (17,455,425 to 17,460,926, reverse strand). Ensembl gene ENSG00000171773.
Subcellular location: Cytoplasm (Isoform 1); Mitochondrion; Cell projection, cilium, photoreceptor outer segment (Isoform 2)
Gene Ontology:
Molecular function: protein binding; receptor ligand activity
Biological process: cell redox homeostasis; photoreceptor cell maintenance; response to oxidative stress; response to photooxidative stress; signal transduction
Cellular component: cytoplasm; mitochondrion; photoreceptor outer segment
Genetic constraint (gnomAD): Loss-of-function variants: 6 observed, 8.1 expected, observed/expected ratio (o/e) 0.74, 90% interval 0.4 to 1.45. That is too few expected variants to judge how well the gene tolerates losing a copy. Missense variants: 277 observed, 242.99 expected, observed/expected ratio (o/e) 1.14, 90% interval 1.03 to 1.26. Synonymous variants: 123 observed, 111.79 expected, observed/expected ratio (o/e) 1.1, 90% interval 0.95 to 1.28.
Homologues: Orthologues: chimpanzee NXNL1 (100% identical), dog NXNL1 (85% identical), pig NXNL1 (83% identical), mouse Nxnl1 (78% identical), rat Nxnl1 (75% identical), zebrafish nxnl1 (51% identical), Caenorhabditis elegans R05H5.3 (20% identical), Caenorhabditis elegans trx-3 (15% identical). Paralogues in human: NXNL2 (23% identical), NXN (20% identical).
Diseases named in the same sentence as NXNL1 in open-access papers:
NXNL1 is named in the same sentence as 9 diseases in open-access papers, as found by Europe PMC text mining. Sharing a sentence is not in itself a finding about the gene and the disease. The quoted sentences say what the papers report.
retinitis pigmentosa (7 papers, 2011 to 2024). Retinitis pigmentosa (RP) is an inherited retinal dystrophy leading to progressive loss of the photoreceptors and retinal pigment epithelium and resulting in blindness usually after several decades. "Nxnl1, a viability factor in eye development that is associated with retinitis pigmentosa and Bardet-Biedl syndrome, is also involved in suppression of oxidative stress and possessed a similar pattern of expression." (PMID 30389848, 2018).
retinal degeneration (3 papers, 2011 to 2023). Degeneration of the retina. "Group (b) was very small with only 9 genes, and it did not make a cluster of functionally related GO terms, although 6 of 9 genes were annotated as causal genes for retinal degeneration (Abca4, Elovl2, Fscn2, Nxnl1, Pde6c, and Pde6h)." (PMID 24747725, 2014). "Interestingly, we reported recently that TAU is hyperphosphorylated in the retinal degeneration mouse model carrying an inactivation of the Nxnl1 gene encoding the cone viability factor RdCVF." (PMID 22174898, 2011).
retinal detachment (1 paper, 2019). An eye emergency condition which may lead to blindness if left untreated. "The expression of the NXNL1 gene, encoding for RdCVF, is decreased following retinal detachment, which leads to a lack of trophic support for cones." (PMID 30696106, 2019).
retinoblastoma (1 paper, 2010). A malignant tumor that originates in the nuclear layer of the retina. "With the NXNL1 transfection series and Y79 retinoblastoma cells, we found similar levels of reporter activity with the −2072 to +57 bp, −1034 to +57 bp, and −501 to +57 bp constructs." (PMID 20949100, 2010).
neurodegenerative disease (1 paper, 2011). A disorder of the central nervous system characterized by gradual and progressive loss of neural tissue and neurologic function. "Interestingly, RdCVF is encoded by the Nucleoredoxin-like gene, Nxnl1 that belongs to the family of thioredoxin proteins, reducing oxidative stress, a condition encountered broadly in neurodegenerative diseases." (PMID 22185426, 2011).
NXNL1 also shares sentences with these, for which no sentence is quoted: age-related macular degeneration (1 paper); Bardet-Biedl syndrome (1); cancer (1); retinitis (1).